HIF1A (hypoxia inducible factor 1 subunit alpha)
Diseases named in the same sentence as HIF1A in open-access papers (continued):
Sharing a sentence is not in itself a finding about the gene and the disease.
tumor (continued). "Inhibition of the transcription factor HIF-1α has been repeatedly suggested as a therapeutic target against cancer, because of its key role in the Warburg effect could allow fine control of tumor growth." (PMID 26252771, 2015). "In preclinical studies, inhibition of HIF-1α activity has marked effects on tumor growth; inhibitors of HIF-1α have therefore attracted much attention as new therapeutic agents for patients with advanced malignancies, and several clinical studies have been performed." (PMID 25733977, 2015). "In this cohort, 86/147 patients had detectable HIF-1α in their primary resected tumours." (PMID 24563687, 2014). "It is well known that HiF-1α accumulates in most of tumor cells." (PMID 25338163, 2014). "Although decreasing activity of HIF-1α and/or MMPs by reducing tumor hypoxia could be an effective strategy in cancer treatment, there is currently no effective way of achieving reduction of hypoxia in tumors." (PMID 24988190, 2014). "Moreover, activation of Akt/mTOR pathway appears to stimulate accumulation and decrease degradation of HIF-1α in hypoxic tumor cells." (PMID 25140303, 2014). "Because of this function, Hif1α plays a fundamental role in tumor progression." (PMID 25126540, 2014). "We were able to detect HIF-1α proline-hydroxylation in 79% of human tumours expressing HIF-1α." (PMID 24563687, 2014). "In central areas of tumors, where tumor cells displayed an epithelial phenotype, β-catenin was found mainly associated with the membrane (16/16 cases, 100%), while weak or absent staining was observed for GRP78 (14/16 cases, 88%) and HIF1α (16/16 cases, 100%) in all tumor cells." (PMID 24498091, 2014). "In addition, high RBP2 expression was closely associated with tumor size, high HIF-1α expression, high VEGF expression and increased tumor angiogenesis." (PMID 25162518, 2014). "In order to evaluate whether disruption of the HIF-1α/p300 complex by ETPs affected the growth of human tumor xenografts, PC3 cells were implanted subcutaneously into severe combined immunodeficiency (SCID) mice." (PMID 24775564, 2014). "The large numbers and wide range of tumours that express proline-hydroxylated HIF-1α suggest that the increased levels of hydroxylated HIF-1α, which is likely transcriptionally active, is an important part of the physiological hypoxia sensing mechanism in moderate levels of hypoxia." (PMID 24563687, 2014). "The inhibition of aerobic glycolysis or HIF-1α expression using genetic manipulation or chemical inhibitors may sensitize tumor cells to chemotherapy." (PMID 24658058, 2014). "Taken together, these results indicate that IMQ may activate STAT3 to increase HIF-1α mRNA expression and may stimulate Akt to promote HIF-1α protein synthesis through ROS in tumor cells." (PMID 24658058, 2014). "Finally, we demonstrated that the inhibition of both glycolysis and HIF-1α expression is a useful strategy to enhance the anti-tumor activity of IMQ in vitro and in vivo." (PMID 24658058, 2014). "HIF-1α is a master transcription factor for angiogenesis in tumor." (PMID 25548899, 2014). "Although previous studies have reported that Celastrol has the potential to inhibit HIF-1α mRNA transcription and suppress hypoxia-induced angiogenesis and tumor metastasis, in this study, we found that a short amount of time exposure of Celastrol did not affect the HIF-1α mRNA levels." (PMID 25383959, 2014). "All of these evidences indicated that the mechanisms of BAG3 in impacting the progression of tumor may involve the HIF-1α signaling pathway." (PMID 24895585, 2014).
tumor (continued). "In addition, expression of the hypoxia-inducible transcription factor HIF-1α was also significantly reduced in the tumors of platelet-depleted mice, suggesting that platelets are involved in tumor hypoxia." (PMID 24606812, 2014). "It is thought that this might be a novel molecular regulation mechanism through which miR-20b regulates HIF-1α and VEGF but which is also self-regulated by HIF-1α so that tumour cells continuously adapt to different oxygen concentrations." (PMID 25197665, 2014). "Importantly, 20(S)-Rg3, at low doses, exerted similarly effective inhibitory activity in vivo against tumor intraperitoneal spread via reducing HIF-1α protein level and reversing EMT process." (PMID 25197976, 2014). "Therefore, it is difficult to rescue a miR-18a-mediated suppressive effect on tumor growth and metastasis by ectopic HIF1A expression in LM-miR-18a cells." (PMID 25069832, 2014). "On the other hand, increased TFPI1 at the tumor site may reduce thrombin, leading to hypoxia and the subsequent expression of HIF1α, a potent driver of angiogenesis and invasive cancer." (PMID 24489651, 2014). "The expression of proline-hydroxylated and non-hydroxylated HIF-1α may explain why some studies fail to find a correlation between high HIF-1α tumour levels and adverse clinical outcome." (PMID 24563687, 2014). "Overexpression of HIF1α in some PCa tumor cell lines promoted EMT that was dependent on β-catenin." (PMID 25566502, 2014). "Since HIF-1α expression is induced under hypoxic conditions and melatonin significantly reduced tumor O2 uptake, it may be that melatonin stimulated HIF-1α expression by inducing tumor hypoxia during the dark phase under circadian-regulated conditions." (PMID 25099274, 2014). "Hypoxia, a common feature of the cancer microenvironment, promotes prometastatic mechanisms such as the upregulation of hypoxia-inducible factor (HIF)-1α, a transcriptional master regulator that enhances cancer cell metastatic potential, angiogenesis, and tumor cell invasion and migration." (PMID 24634093, 2014). "Tumor microenvironmental hypoxia induces hypoxia inducible factor-1α (HIF-1α) overexpression, leading to the release of lysyl oxidase (LOX), which crosslinks collagen at distant sites to facilitate environmental changes that allow cancer cells to easily metastasize." (PMID 25238333, 2014). "This suggested that the upregulation of HIF-1α could not only promote tumor growth, but also enhance the ability of tumor invasion." (PMID 25013467, 2014). "The RBP2 protein may play a critical role in NSCLC tumor angiogenesis by enhancing HIF-1α and VEGF expression under normoxia via the PI3K/Akt signaling pathway." (PMID 25162518, 2014). "Interestingly, we found that this tumor microenvironment can also be altered by the absence or presence of macrophage HIF-1α or HIF-2α." (PMID 25295611, 2014). "In agreement with findings that ROS may regulate angiogenesis and tumor growth through HIF-1α and VEGF, over-expression of Nrf2 in tMSC led to a diminished hypoxic response through destabilization of HIF-1α and reduced VEGFA and ADM expression." (PMID 24491031, 2014). "Recently, lysyl oxidase (LOX) has been identified as an important regulator of hypoxia-induced tumor progression via an HIF-1α-dependent mechanism in a variety of human cancers including breast, colon, head and neck, ovarian, prostate and renal cell carcinomas." (PMID 25174950, 2014). "As an upstream regulator of HIF1A, miR-18a function is likely tumor type–dependent." (PMID 25069832, 2014). "Knowing that metastases develop from circulating tumor cells escaping the primary site of cancer during their passage in the blood stream, these cells switch from a hypoxic to a normoxic environment and escape regulation by HIF-1α." (PMID 24629239, 2014). "Because Cx43 can inhibit HIF-1α-mediated transcriptional activation, the difference in hypoxic responsiveness in tumor cells may be correlated with their Cx43 status." (PMID 25548899, 2014).
tumor (continued). "Our conclusions are that the degradation of proline-hydroxylated HIF-1α may be rate-limited in tumours and therefore provides new insights into mechanisms of HIF upregulation." (PMID 24563687, 2014). "The aim of our study was to investigate the posttranslational modification of HIF-1α in tumours, to assess whether there are additional mechanisms besides reduced hydroxylation leading to stability." (PMID 24563687, 2014). "HIF1α-positive cells were prominent at tumor margins and surrounding areas of neovascularization, implying that up-regulation of HIF1α was an early molecular event in carcinogenesis and tumor invasiveness." (PMID 24567056, 2014). "Like BAG3, HIF-1α staining was significantly associated with tumor TNM stage (P = 0.012), but not with tumor size (P = 0.22)." (PMID 24895585, 2014). "However, considering our observation that HIF-1α overexpression rescued the cell from the anti-HCC activity of miR-338-3p, it is likely that regulation of HIF-1α by miR-338-3p is a key anti-tumor aspect in HCC." (PMID 25531114, 2014). "Previous reports showed that Tβ4 protein could lead in a tumor cell microenvironment to hypoxic condition enhancing HIF-1α stabilization." (PMID 25271630, 2014). "We observed IMQ-induced aerobic glycolysis and HIF-1α expression in several tumor cell lines." (PMID 24658058, 2014). "In addition, this work demonstrates that Rb plays a hitherto unidentified role in tumor suppression by virtue of effects on HIF1α/β that is distinct from its classic tumor suppressor role mediated through repression of E2F transcription factors." (PMID 24919196, 2014). "Briefly, a crosstalk between HIF-1α and Cav-1 induces autophagy/mitophagy in the tumor stroma, and consequently provides cancer cells with essential amino acids and nucleotides to drive tumor growth and metastasis." (PMID 24978438, 2014). "The findings also indicate that miR-199a may have high therapeutic efficiency as a tumor suppressor by targeting both HIF-1α and COX-2." (PMID 24413338, 2014). "It was found that cellular growth and survival activities decreased in SaOS-2 cells transfected with shRNA targeting HIF-1α under hypoxia, and the rates of formation and growth of xenograft tumours in mice transfected with shRNA targeting HIF-1α slowed significantly." (PMID 24895555, 2014). "Inhibition of HIF-1α expression may lead to inhibition of cell proliferation and growth, induction of apoptosis, and prevention of tumor progression." (PMID 24618817, 2014). "For example, hypoxia (HIF1α), epithelial-mesenchymal transition, inflammatory cytokines (e.g., IL-6 and TGFβ), and embryonic microenvironments can all promote the reprogramming of CCs and increase the overall stemness of the tumor." (PMID 24955094, 2014). "Previous studies have demonstrated that the overexpression of HIF-1α may contribute to the pathogenesis of tumor resistance to chemotherapy." (PMID 25310259, 2014). "The hypoxic tumour microenvironment contributes to tumour progression by activating a series of adaptive responses that include tumour neovascularisation and tumour-specific immune responses, mediated through the key transcriptional regulators HIF-1α and HIF-2α." (PMID 24162378, 2014). "The resulting hypoxic condition (PO2<10 mmHg [∼1.5% O2]) prevents degradation of hypoxia-inducible factor-1α (HIF-1α) through VHL tumor suppressor, allowing trans-activation of pro-angiogenic factors, among which the most notable is vascular endothelial growth factor (VEGF)." (PMID 24918449, 2014). "The association between HIF-1α and MMP2 expression in tumor tissues has rarely been studied." (PMID 25013467, 2014). "No significant improvement in accuracy was obtained by combining TG2 with HJURP or HIF-1α in either tumor cells or in stroma, whereas an important increase in accuracy (AUC 0.80, 95% CI 0.63–0.97) was obtained when HIF-1 α and HJURP stromal expression was considered together." (PMID 25243117, 2014).
tumor (continued). "Therefore, from a novel point of view, our findings provide one more piece of strong evidence for the suppressive role of p27 in the process of tumor promotion and progression in arsenic response, which is achieved by inhibition of HIF-1α protein translation." (PMID 25412313, 2014). "This event was accompanied by the synergistic inhibition of CRAF, pMEK, kinase suppressor of RAS (Ksr), hypoxia-inducible factor 1-α (HIF-1α), the metabolic enzyme hexokinase II (Hxk II) and the transcription factor specificity protein 1 (Sp1), along with reduction of tumor volume in vivo." (PMID 24920406, 2014). "However, understanding how fluctuating miR-18a and HIF1A levels ultimately drive metastasis from the primary tumor to reduce survival requires further investigation." (PMID 25069832, 2014). "Therefore, our results confirmed that RBP2 is a non-hypoxic inducer of HIF-1α expression that modulates the process of tumor angiogenesis via HIF-1α-VEGF signaling." (PMID 25162518, 2014). "It has been proposed that HIF-1α inhibition could be an effective strategy to block tumour progression and clinical trials are underway to test novel compounds that could do so." (PMID 24835245, 2014). "Evidence on this concept is further warranted, and more future research work is needed to elucidate whether our findings can be explained by stage specificity role of HIF1A SNPs in tumor progression." (PMID 24567056, 2014). "Considering the fact HIF-1α promotes the Warburg effect, it is somewhat problematic to mechanistically reconcile melatonin-induced stimulation of HIF-1α expression during either the circadian dark phase or tumor perfusion when aerobic glycolysis was actually diminished." (PMID 25099274, 2014). "Indeed, hypoxia, through HIF-1α, usually promotes stem-like features providing a niche for tumor-initiating cells." (PMID 24550888, 2014). "Tumor coagulation and HIF-1α orHSP70 expression were assessed 24 hr post-RFA." (PMID 25133740, 2014). "However, some miRs such as miR-503 downregulated by HIF-1α inhibit tumor angiogenesis by targeting FGF2 and VEGF." (PMID 24914051, 2014). "Furthermore, miR-338-3p sensitized HCC cells to sorafenib in vitro and in a HCC subcutaneous nude mice tumor model by inhibiting HIF-1α." (PMID 25531114, 2014). "In 8/30 patients (26.7%), HIF-1α positivity was found in tumor cells." (PMID 24460801, 2014). "In addition, AM expression gets rapidly activated by hypoxia through a HIF-1α mediated mechanism, thus characterizing AM as a major survival factor for tumour cells." (PMID 25475159, 2014). "Collectively, our data supported that LCN2, which was able to detect HIF-1α-positive tumor cells, may be a useful plasma marker for hypoxic tumors." (PMID 25467539, 2014). "Activation of HIF-1α (Hypoxia-inducible factor 1-α) leads to a glycolytic switch in the tumour cell metabolism pathway, resulting in increased production and export of lactic and carbonic acids to the extracellular space, and leads to a decline in extracellular pH (pHe)." (PMID 25547490, 2014). "Interestingly, the mice in this study were able to synthesize their own ascorbate, and the control group also had reduced tumor growth compared to the mutant HIF-1α group." (PMID 25540771, 2014). "Overexpression of HIF-1α is significantly correlated with histology, depth of invasion and poor prognosis for patients with GC, and may be utilized for tumor-specific molecular target-based therapy." (PMID 24765145, 2014). "The underlying mechanism(s) leading to the accumulation of proline-hydroxylated HIF-1α in tumours is unknown." (PMID 24563687, 2014). "However, there was significant correlation between MMP2 or HIF-1α protein expression and tumor size, metastasis, presence of a capsule and clinical TNM staging of HCC." (PMID 25013467, 2014). "Furthermore, HIF-1α is highly expressed in many tumors due to hypoxia-dependent and -independent mechanisms and is correlated with tumor growth and a more aggressive tumor phenotype." (PMID 25365172, 2014).
tumor (continued). "Third, the induction of HIF-1α mediated IMQ-induced apoptosis in tumor cells." (PMID 24658058, 2014). "ERK/MAPK signal transduction pathway can regulate the expression of HIF-1α, and the expression of HIF-1α may regulate the expression of target gene associated with tumor." (PMID 24976852, 2014). "Taken together, these results may suggest an inverse correlation between the protein expression of Cx43 and HIF-1α in murine tumor cells." (PMID 25548899, 2014). "Similarly, we demonstrate that tumor cells with lower Cx43 expression exhibited higher HIF-1α-dependent gene expression." (PMID 25548899, 2014). "In echinomycin-treated tumor tissues, HIF-1α expression was decreased." (PMID 24914051, 2014). "Because HIF-1α regulates a variety of processes, such as angiogenesis and glucose metabolism, this subunit is broadly accepted as a critically important tumor cell survival factor that is required for tumorigenesis and metastasis in early and late stages of tumors, respectively." (PMID 25249371, 2014). "Hypoxia-inducible factor 1-alpha (HIF-1α) and CA-IX are hypoxia tumor markers." (PMID 25100134, 2014). "HIF-1α is an important transcription factor that renders tumor cells to adapt to hypoxia." (PMID 24662981, 2014). "HIF-1α is an important transcriptional factor and plays a crucial role in tumor angiogenesis." (PMID 25162518, 2014). "Inactivation of GSK-3β and downregulation of ΔNp63 by wogonin enhances apoptosis effect in human nasopharyngeal carcinoma cells through.Wogonin inhibits tumor angiogenesis via degradation of HIF-1α protein in four human tumor cell lines, including MCF-7, MDA-MB-231, HepG2, and HCT116." (PMID 24786691, 2014). "Tumor hypoxia was measured by immunohistochemistry as the percentage of carbonic anhydrase IX (CA-IX)-positive cells and by real-time quantitative PCR (qPCR) as the expression of hypoxia-inducible factor-1α (HIF-1α)." (PMID 24500694, 2014). "It suggests that the regulatory feedback loop between PIM2 and HIF-1α may facilitate tumor cells to adapt to hypoxia." (PMID 24505470, 2014). "Of note, silencing of HIF-1α also induced suppression of tumor cell invasiveness and migration." (PMID 25068796, 2014). "HIF1α, activated under hypoxic conditions, promotes aggressive tumor cell invasion and metastasis." (PMID 25566502, 2014). "YC-1 is also a HIF-1α inhibitor, so YC-1 may play a assisting role in anti-tumor of sorafenib through the mechanism above, which confirms us that sorafenib-YC-1 combination could be potential for use for HCC patients in near future." (PMID 24418169, 2014). "Of note, mTOR inhibitor temsirolimus has also demonstrated evidence of HIF-1α inhibition, and a clinical trial combining temsirolimus with bevacizumab and liposomal doxorubicin demonstrated extensive anti-tumor activity in multiple tumor types." (PMID 25373733, 2014). "Next, we evaluated the control mechanisms of IMQ-induced HIF-1α expression in tumor cells." (PMID 24658058, 2014). "In tumours where proline-hydroxylated HIF-1α is detected, 29% are mono-hydroxylated at Pro402, 20% at Pro564 and 51% of tumours are proline-hydroxylated at both sites, highlighting biological heterogeneity between tumours." (PMID 24563687, 2014). "Thus, HIF-1α inhibition in combination with anti-angiogenic therapy is a promising strategy for targeting tumor resistance." (PMID 25373733, 2014). "HIF1A activation by hypoxia has been identified as a key event for continuous expansion of tumor mass and metastasis by stimulating angiogenesis and activating the expression of metastatic signature genes in various types of tumor cells." (PMID 25069832, 2014). "The association between HIF-1α and proliferation is not fully understood - perhaps HIF-1α may either reflect or react to tumor proliferation." (PMID 25421331, 2014). "Indeed, the ratio between the maximal value of the oscillations and the normoxic stationary level of HiF-1α is equal to 3.2 for tumor cells, and to 2.5 for normal cells." (PMID 25338163, 2014).